LINC02418 (long independently transcribed non-coding RNA 2418)
Gene: Long non-coding RNA gene on chromosome 12 (130,018,131 to 130,045,069, reverse strand). Ensembl gene ENSG00000214039.
Diseases named in the same sentence as LINC02418 in open-access papers:
LINC02418 is named in the same sentence as 3 diseases in open-access papers, as found by Europe PMC text mining. Sharing a sentence is not in itself a finding about the gene and the disease. The quoted sentences say what the papers report.
colorectal cancer (3 papers, 2022 to 2025). A primary or metastatic malignant neoplasm that affects the colon or rectum. "In addition, LINC02418 is overexpressed in colorectal cancer tissues, cell lines, and serum exosomes, suggesting the likelihood of the origin of exosomal LINC02418 from cancer cells." (PMID 35055115, 2022). "Recently, although there are some explorations for LINC02418 in colorectal cancer, all previous studies only focused on the ceRNA mechanism and the intricate mechanism of LINC02418’s participation in colorectal cancer is still not thoroughly understood." (PMID 40082414, 2025).
tumor (2 papers, 2020 to 2025). "Firstly, we are the first to determine that LINC02418 activates the Wnt signaling pathway, a critical pathway in tumor progression, which highlights a previously unrecognized role of LINC02418 in CRC." (PMID 40082414, 2025). "Knockdown of LINC02418 decreased the CRC cell growth in vitro and in vivo and limited cell migration and invasion ability, indicating that LINC02418 was able to promote CRC progress and might have a vital role in regulating tumor development-associated signaling pathways." (PMID 32973404, 2020).
LINC02418 also shares sentences with these, for which no sentence is quoted: cancer (2 papers).